PLXNA4 (plexin A4)
Diseases named in the same sentence as PLXNA4 in open-access papers (continued):
Sharing a sentence is not in itself a finding about the gene and the disease.
tumor (17 papers, 2014 to 2025). "The top genes significantly upregulated in tumor NK cells compared to NK cells in all other tissues included genes with a variety of functions, including PLXNA4, known to be upregulated in NK cells that have been reprogrammed after exposure to malignant cells." (PMID 41208961, 2025). "More specifically, PLXNA4 plays a role in the tumor microenvironment by negatively regulating the migration and proliferation of cytotoxic T cells (CTLs), thus limiting their potential to infiltrate tumors and limit cancer progression." (PMID 41562091, 2025). "Cohort-specific validation by immunohistochemistry on well-annotated tumor microarray with survival endpoints will be necessary to establish prognostic value and to support PLXNA4 as a PCa biomarker." (PMID 41562091, 2025). "In non-small cell lung cancer (NSCLC), miR-564 is directly targets the PLXNA4, leading to suppression of proliferation, migration, invasion, and tumor growth." (PMID 41562091, 2025). "Compared with mice that received WT T cells, those that received Plxna4-KO T cells exhibited significantly slower tumor growth and a significantly higher number of tumor-infiltrating CD8+ T cells." (PMID 38329122, 2024). "Since Sema6D derived from nonhematopoietic cells seemed to regulate CD8+ T cell function in the TME, we investigated the role of Plexin-A1 and Plexin-A4, which are receptors for Sema6D, in T cells isolated from tumor-draining LNs." (PMID 38329122, 2024). "PLXNA4 has been demonstrated to promote tumor progression and tumor angiogenesis by enhancing the signaling of VEGF and bFGF." (PMID 39684481, 2024). "We have previously observed that silencing the expression of plexin-A4 in U87MG inhibits the proliferation of U87MG cells as well as their tumor forming ability." (PMID 36658114, 2023). "PLXNA4 inhibits tumor cell migration, induces innate immune responses via working with Toll-like receptor, and is also co-downregulated with IQGAP1 in PC." (PMID 33498739, 2021). "Plxna4 reportedly promotes tumour progression and tumour angiogenesis by enhancing VEGF and basic fibroblast growth factor signalling." (PMID 24702795, 2014). "PLXNA4 mutations, more frequent in R patients, have been shown to promote Cytotoxic T-lymphocyte infiltration in pre-clinical tumor models, as PLXNA4 behaves as a negative checkpoint regulating T-cell migration and proliferation." (PMID 37739939, 2023). "PLXNA4 and PLXNB1 had significantly increased expression in subtype C5, suggesting an association between higher gene expression and favorable immune infiltrate type, indicating a tumor suppressor role." (PMID 32640719, 2020). "PLXNA4 may promote progression and angiogenesis of tumor, possibly by enhancement of VEGF and bFGF signaling pathways." (PMID 30841487, 2019). "Here the authors investigate how these interactions affect CD8+ T cells in tumour immunity, showing that NRP-1, Plexin-A1 and Plexin-A4 are upregulated on T cells allowing tumour derived SEMA3A to inhibit CD8+ T cell migration and function." (PMID 38609390, 2024). "Here we demonstrate that Neuropilin-1 (NRP1) and Plexin-A1 and Plexin-A4 are upregulated on stimulated CD8+ T cells, allowing tumour-derived SEMA3A to inhibit T cell migration and assembly of the immunological synapse." (PMID 38609390, 2024). "We have found previously that plexin-A4 silencing also inhibits the proliferation of U87MG cells and tumor formation from these cells." (PMID 36658114, 2023). "PLXNA4 forms complexes with fibroblast growth factor receptor 1 (FGFR1) and vascular endothelial growth factor receptor 2 (VEGFR-2) to boost basic fibroblast growth factor (bFGF)/VEGF pathways, promoting proliferation and tumor growth." (PMID 41562091, 2025).
tumor (continued). "An ex vivo experiment using T cells from tumor-draining lymph nodes (LNs) demonstrated that recombinant Sema6D (rSema6D) inhibited T cell activation and proliferation induced by anti-CD3/anti-CD28 stimulation, and this inhibitory effect was partially decreased in Plxna4-KO T cells." (PMID 38329122, 2024).
cancer (7 papers, 2013 to 2025). A tumor composed of atypical neoplastic, often pleomorphic cells that invade other tissues. "The genes PLXNA1, PLXNA2 and PLXNA4 are enriched in cellular development - axon guidance processes and 68 pan-cancer mutations show a significant clustering of mutations, near a predicted functional site (i.e. based on the most highly conserved positions within the FunFam) and an IBIS PPI site." (PMID 30670742, 2019). "One cluster includes SEMA3D, SEMA3E, SEMA3G and PLXNA4, which all showed primarily down-regulation in the tested cancer tumors." (PMID 32640719, 2020). "We observed that levels of these genes showed great heterogeneity in different cell lines as in patient tumors, with PLXNA1 having the highest expression and PLXNA4 having the lowest expression across all cancer cell lines." (PMID 32640719, 2020). "Both NRPs, PLXNA1-A3, PLXNB1-B2, and PLXND1 had relatively higher expression and smaller heterogeneity, while genes PLXNA4, PLXNB3 and PLXNC1 had lower expression across all cancer types but with higher heterogeneity." (PMID 32640719, 2020). "For stromal score, NRP1 showed the highest positive correlation across all cancer types (r = 0.59), followed by PLXND1 (r = 0.54), NRP2 (r = 0.50), PLXNC1 (r = 0.48) and PLXNA4 (r = 0.28) (p < 0.0001)." (PMID 32640719, 2020).
infection (2 papers, 2021 to 2024). The state of being infected such as from the introduction of a foreign agent such as serum, vaccine, antigenic substance or organism. "Furthermore, proteins related to the cytoskeleton and cytoskeleton remodeling (KRT2 and PLXNA4) and genes coding for components of the cytoskeleton, KRT13 (LOC100515166), KRT17 (LOC100737113), KRT6A, and BFSP1, were significantly higher expressed after infection with swH1N1 compared to huH1N1." (PMID 39247193, 2024).
bacterial infection (1 paper, 2021). "It is hypothesized that these Plxna4+ superficial urothelial cells may act as ‘whistleblower cells’ that are involved in the initiation of host response during bacterial infection." (PMID 33538002, 2021).
PLXNA4 also shares sentences with these, for which no sentence is quoted: pulmonary fibrosis (4 papers); autism spectrum disorder (3); Parkinson disease (3); neurodevelopmental disorder (2); dementia (1); epilepsy (1); essential tremor (1); fibrosarcoma (1); Huntington disease (1); idiopathic pulmonary fibrosis (1); immune disease (1); lung carcinoma (1); mastitis (1); metastatic colorectal cancer (1); metastatic tumors (1); movement disorder (1); neuroblastoma (1); neurological diseases (1); Onset (1); Parkinson’s (1); psychiatric disorder (1); venous thromboembolism (1).